Y_RNA (Y RNA )
Gene: Miscellaneous RNA gene on chromosome 4 (139,200,395 to 139,200,513, forward strand). Ensembl gene ENSG00000207384.
Homologues: Orthologues: chimpanzee Y_RNA (100% identical), macaque Y_RNA (96% identical). Paralogues in human: RNY1 (81% identical), Y_RNA (80% identical), Y_RNA (79% identical), Y_RNA (78% identical), Y_RNA (77% identical), RNY1P11 (76% identical), Y_RNA (76% identical), Y_RNA (75% identical), RNY1P8 (74% identical), Y_RNA (74% identical), RNY1P10 (73% identical), Y_RNA (73% identical), and 91 more.